RNU6-840P (RNA, U6 small nuclear 840, pseudogene)
Gene: Small nuclear RNA gene on chromosome 17 (35,093,909 to 35,093,973, forward strand). Ensembl gene ENSG00000253084.
Homologues: Orthologues: chimpanzee U6 (100% identical), macaque U6 (97% identical), dog U6 (86% identical), rabbit U6 (85% identical). Paralogues in human: RNU6-329P (94% identical), RNU6-38P (94% identical), RNU6-1011P (92% identical), RNU6-1145P (92% identical), RNU6-1322P (92% identical), RNU6-187P (92% identical), RNU6-338P (92% identical), RNU6-33P (92% identical), RNU6-468P (92% identical), RNU6-658P (92% identical), RNU6-682P (92% identical), RNU6-774P (92% identical), and 1285 more.